CXCR4 (C-X-C motif chemokine receptor 4)
Diseases named in the same sentence as CXCR4 in open-access papers (continued):
Sharing a sentence is not in itself a finding about the gene and the disease.
lung carcinoma (continued). "Furthermore, both proteins were correlated with poor survival in non-small-cell lung cancer patients, while only CXCR4 was associated with worse survival in small-cell lung cancer patients, suggesting that JUNB and CXCR4 are potentially important prognostic biomarkers for lung cancer." (PMID 36612166, 2022). "C-X-C motif chemokine ligand 12 (CXCL12), also known as the sole ligand of CXCR4, has been verified to be expressed in many tissues and cell types Previous studies demonstrated that the positive expression rate of CXCL12 in lung cancer was 31.3–80%." (PMID 35729596, 2022). "Furthermore, CXCR4 expression might be a valuable predictor for tumor recurrence in lung cancer." (PMID 35397601, 2022). "In our study, the survival of advanced lung cancer treated with immunotherapy was significantly reduced in those patients with high baseline levels of CCR9+ or CCR10+ CD4+ T cells, or CXCR4+ CD8+ T cells." (PMID 35740564, 2022). "Similar to CXCR4 and β-catenin, PPARδ inhibitor also blocked the EMT-promoting effect of SDF-1 on lung cancer cells." (PMID 33637678, 2021). "The elevation of circFGFR1 reduces PD-1-positive lung cancer cell and CD8+ T cell frequency by regulating the miR-381-3p/C-X-C motif chemokine receptor 4 (CXCR4) axis, which is responsible for reduced sensitivity to anti-PD-1 antibodies." (PMID 32171304, 2020). "While CXCR4 is known to promote EMT, the depletion of CXCR7 alone is sufficient to reverse the EMT phenotype in lung cancer models." (PMID 32260318, 2020). "First, we explored CXCR4 and CXCR7 expression in human lung cancer specimens and cell lines by immunohistochemistry, western blot and flow cytometry." (PMID 33129326, 2020). "Our study proved that ERα in lung cancer cells can promote the signal cross‐talk between lung cancer cells and macrophages via the ERα/CCL2/MMP9 and CXCL12/CXCR4 pathways." (PMID 32356397, 2020). "In the present study, CXCR4 was induced by hypoxia, which was important for the EMT and acquisition of stemness in lung cancer." (PMID 30760238, 2019). "The expression of miR-1246 was downregulated in lung cancer cell lines and cervical cancer tissue, was negatively correlated with the clinical stage and inhibited cell invasion and the EMT by targeting CXCR4." (PMID 31552107, 2019). "CXCR4, CK7, CDH1, CTNNB1 and HIF1A showed significant upregulation in primary lung cancer as compared to liver metastasis." (PMID 30383826, 2018). "Over the last few decades, increasing numbers of studies have shed more light on specific surface biomarkers of CSCs in lung cancer, including CD44, CD133, aldehyde dehydrogenase 1 (ALDH1), C-X-C chemokine receptor type 4 (CXCR4), and ABCG2." (PMID 28903328, 2017). "In H661 and H1299 lung cancer cells, Western blot analysis demonstrated that diminished CD164 expression resulted in decreased Akt and mTOR phosphorylation, and decreased CXCR4 activation." (PMID 28903328, 2017). "H1299 xenografts in nude mice and lung cancer tissues from patients were used for immunohistochemistry to detect the expression and distribution of HIF-1α, CXCR4 and SDF-1α." (PMID 25843954, 2015). "The results clearly demonstrated that not only CXCR6 and CXCR4 (30/33) but also CXCL12 and CXCL16 (19/33) were coexpressed in both human primary lung caner tissues and lung cancer cell lines." (PMID 24897301, 2014). "It was demonstrated that similar to CXCL12 and CXCR4, CXCL16 and CXCR6 were also coexpressed in human primary lung cancer tissues." (PMID 24897301, 2014). "Increasing evidence also indicates that the CXC chemokine receptor 4 (CXCR4)/chemokine CXC motif ligand 12 (CXCL12) chemokine axis is important for the cell invasion and migration of lung cancer." (PMID 24944647, 2014). "Thus, we propose that CXCR4 may represent a therapeutic target for lung cancer patients, and that RNAi with siRNA targeting CXCR4 may establish an effective strategy for the treatment of lung cancer." (PMID 24944647, 2014).
lung carcinoma (continued). "CXCR4 and CXCR7 mediate tumor metastasis in several types of cancer (e.g. breast, lung cancer, lymphoma)." (PMID 24416254, 2014). "Markers such as ESA, CXCR4, ALDH and ABCG2 have been used with CD133 for isolating CSC from lung cancers." (PMID 21124918, 2010). "Nevertheless, owing to the complexity of CXCR4 interaction in the TME, combinatorial treatment of CXCR4 with chemotherapy, immunotherapy, or stromal targeting agents is required to achieve maximum therapeutic effect for lung cancer patients." (PMID 41383468, 2025). "Common signal pathways involved with advanced lung cancer, were epidermal growth factor receptor/Kirsten rat sarcoma/anaplastic lymphoma kinase (EGFR/KRAS/ALK) and C-X-C motif chemokine ligand 12/C-X-C motif chemokine receptor 4 (CXCL12/CXCR4)." (PMID 38711158, 2024). "To obtain a more comprehensive understanding of the expression of AFAP1L1 in lung cancer endothelial cells, we assessed the expression density of well-known endothelial cell marker genes (PECAM1), tip cell marker genes (DLL4 and CXCR4) and AFAP1L1 in the t-SNE projection." (PMID 37737201, 2023). "Among the different currently available drugs that inhibit CXCR4 activation, motixafortide—a best-in-class antagonist of this GPCR receptor—has exhibited promising results in preclinical studies of pancreatic, breast, and lung cancers." (PMID 36901829, 2023). "Both JUNB and CXCR4 have been related to metastasis, while to date, evaluation of both JUNB and CXCR4 in lung cancer patients’ CTCs has not been presented." (PMID 36612166, 2022). "The HR from 7 studies including early resected lung cancer (stage I-III) patients and 1 study including metastatic lung cancer (stage IV) patients showed that increased CXCR4 expression predicted poor OS (HR 1.62, 95% CI 1.32–1.98, P < 0.001, I2 = 48.5%; HR 1.67, 95% CI 1.16–2.38)." (PMID 35729596, 2022). "The pooled OR of 7 studies with substantial heterogeneity (I2 = 70.5%) indicated that CXCR4 expression was increased in lung cancer with distant metastasis compared to lung cancer without distant metastasis (OR 3.65, 95% CI 1.53–8.68, P = 0.003)." (PMID 35729596, 2022). "In most lung cancer types, the CXCL12/CXCR4 axis is tumor-promoting." (PMID 36164329, 2022). "It implies that SDF4/CXCR4 complex plays a critical and specific role in chemotherapy-regulated angiogenesis, but not SDF1/CXCR4, and consequently contribute to metastasis of lung cancer." (PMID 33953165, 2021). "Similarly, CXCR7 was scarcely expressed in HUVEC, but up-regulated in A549 and H460, while CXCR4 was expressed in HUVEC, A549 and H460 but was higher in lung cancer cell lines." (PMID 33129326, 2020). "Together, the interactions between lung cancer cells and macrophages through ERα/CCL2/CCR2/MMP9 and CXCL12/CXCR4 pathways could promote the NSCLC progression." (PMID 32356397, 2020). "Further verifying our findings about the pivotal role of both SDF-1 receptors on stabilizing cellular integrity, inhibition of CXCR4 increased TJP-1, occludin, and claudin 5 in the blood/brain barrier in terms of an ischemic stroke and brain-specific metastasis in lung cancer." (PMID 32210974, 2020). "To investigate in vitro the immunosuppressive ability of MICs, we derived lung spheroids from cultures of adherent lung cancer cell lines, showing enrichment in CD133+CXCR4+MICs, and increased expression of CD73 and CD38, an enzyme that also concurs in adenosine production." (PMID 33123122, 2020). "It is not impossible that the overexpression of CXCR4 in lung cancer cells enabled better attachment of tumor cells to the bone." (PMID 33262947, 2020). "Some studies have also revealed the roles of CXCR4, CXCR5 and CCR7 in lung cancer." (PMID 32896997, 2020).
lung carcinoma (continued). "In hypoxia, HIF-1α promotes cell migration and invasion by inducing multiple genes, including the stromal cell-derived factor-1/C-X-C motif chemokine receptor-4 (SDF-1/CXCR-4) axis, C-C motif chemokine receptor 7 (CCR7), and lysyl oxidase (LOX) in lung cancer cells." (PMID 31061665, 2019). "Since SDF-1 can bind to both CXCR4 and CXCR7, we determined CXCR7 expression in lung cancer cell lines and whether IL-24 inhibited CXCR7 in H1299-IL24 cell line." (PMID 25775124, 2015). "The H1299 lung cancer cell line was stably transfected with doxycycline-inducible plasmid expression vector carrying the human IL-24 cDNA and used in the present study to determine the inhibitory effects of IL-24 on SDF-1/CXCR4 axis." (PMID 25775124, 2015). "We showed that the IL-24-mediated inhibitory activity on CXCR4 was comparable when IL-24 was stably induced or expressed transiently in the cancer cell lines and was independent of the lung cancer cell line used." (PMID 25775124, 2015). "By contrast, CXCR4-positive cells were highly invasive in response to CXCL12 and the CXCL12 mediated chemotaxis was dose dependent, indicating that the downregulation of CXCR4 had impaired the ability of the lung cancer cells to migrate." (PMID 24944647, 2014). "The current study also investigated the metastatic potential of lung cancer cell line A549 in response to CXCL12, which may be reduced by the downregulation of CXCR4 expression by the pBSilence1.1 vector, as determined by the Transwell assay." (PMID 24944647, 2014). "In flowcytometry analysis, CD34 and CD45 were expressed extremely low in these lung cancer cell lines (data not shown), while the chemokine receptor CXCR4 was highly expressed in the HTB-182 cell line, but not expressed in the remaining cell lines." (PMID 23738757, 2013). "In summary, this study has provided evidence that amongst reported CSC markers such as CD133, ALDH, CXCR4, ABCG2, ESA and side population staining, CD44 could be a potentially useful marker for lung cancers." (PMID 21124918, 2010). "Compared to circulating blood neutrophils, TANs isolated from early-stage human lung cancer exhibited an activated phenotype, characterized by low CD62L and high CD54 expression, along with a distinct chemokine receptor profile including CCR5, CCR7, CXCR3, and CXCR4." (PMID 41254689, 2025). "This study indicated that positive CXCR4 expression in lung cancer tissue did not significantly impact survival prognosis, highlighting the complexities of utilizing chemokines as standalone therapies in clinical settings despite promising preclinical results in cancer research." (PMID 39114657, 2024). "Similarly, miR-663a has demonstrated upregulated expression across diverse cancer types, such as nasopharyngeal carcinoma, lung cancer, and colon cancer, reflecting its versatile functions in distinct biological contexts and its modulation of pivotal genes, such as p21, TGF-β1, and CXCR4-p21." (PMID 37895471, 2023). "Therefore, we investigated the role of ACKR2, CXCR4, and GPR85 in lung cancer." (PMID 37056937, 2023). "Moreover, CDDP-induced CEBPD enforced the differentiation of fibroblasts toward myofibroblasts in the lung cancer microenvironment and activated the stromal cell-derived factor 4 (SDF4)/C-X-C motif chemokine receptor 4 (CXCR4) to trigger angiogenesis and distal metastasis." (PMID 36776299, 2023). "Our study also proved that CXCR4 was an oncogene under the regulation of ERβ/circ-TMX4/miR-622 signaling to promote lung cancer progression, thus our work established the foundation to target this signaling for developing new drugs for the better treatment of lung cancer." (PMID 35064116, 2022). "However, the CXCR4 was expressed in almost all the cell subsets in both blood and lung cancer tissues, indicating that CXCR4 was not a specific marker for Th17." (PMID 35069521, 2021).
lung carcinoma (continued). "However, so far, it has been found that SDF-1 has two receptors: CXCR4 and CXCR7; Hence, to clarify whether SDF-1 binding to CXCR4 induced lung cancer EMT, RNA interference experiments were carried out to knock down CXCR4 expression in A549 and SPCA-1 cells." (PMID 33637678, 2021). "In this study, we are the first to attempt to systematically investigate the role of CXCR7 independent of CXCR4 in migration, invasion and polarization of lung cancer cell line A549 in vitro and tumor growth and metastasis by establishing animal lung cancer model in vivo." (PMID 33129326, 2020). "However, it is worth pointing out that this knowledge would guide ongoing development and suggest the likelihood of therapeutic benefit for selectively targeting CXCR7 rather than CXCR4 to treat lung cancer." (PMID 33129326, 2020). "In addition, overexpression of CXCR7 increases expression of CXCR4 on the cell surface compared with non-transduced A549 lung cancer cells (data not shown)." (PMID 33129326, 2020). "Then, inhibitor of ERK phosphorylation (U0126, 10 μm), inhibitor of Akt phosphorylation (MK‐2206, 1 μM), as well as the specific antagonist of CXCR4 (AMD3100, 1 μM), were added into THP‐1‐CM, and results show that they can all efficiently reverse CM‐increased ERα expression in the lung cancer cells." (PMID 32356397, 2020). "To further verify the role of NDUFA4 in the growth and metastasis of lung cancer cells, we detected the expression of cell-growth-related molecules including CDK2, CDK3, CDK4, and CDK6, as well as metastasis-related molecules including CXCR4, E-Cadherin, MMP2, MMP3, and MMP9, respectively." (PMID 28325285, 2017). "Furthermore, we found that elevated co-expression of pan-cytokeratin and CXCR4 may be a prognostic marker for patients with advanced disease, as most patients in this study had stage III or IV lung cancer." (PMID 19563666, 2009). "Furthermore, the expression pattern of CXCL16-CXCR6 was similar to that of CXCL12-CXCR4, the specific staining for both CXCR4 and CXCL12 could also be observed in three lung cancer cell lines despite of the difference of expression intensity in different cells." (PMID 24897301, 2014). "A meta‐analysis in all lung cancer tissues containing adenocarcinoma (LUAD) found that the expression of ACKR2 but not the other candidate receptors, CXCR4 and GPR85, was up-regulated in lung cancer studies." (PMID 37056937, 2023). "In clinical lung cancer samples, CXCR7 expression was almost not detected in normal tissue but upregulated in lung tumor tissue, whereas, CXCR4 was highly expressed in both normal and tumor tissues." (PMID 33129326, 2020). "Our finding, that CXCR4 overexpression in tumors is not prognostic of outcomes in SCLC, contrasts with several recent meta-analyses of biomarker levels and lung cancer clinical outcomes." (PMID 28299514, 2017). "Individuals with CXCR4 overexpression have reduced overall survival (OS) and disease-free survival (DFS), and it seems that the high CXCR4 expression has a negative influence, especially in stage III and IV lung cancer, correlated with metastasis to the brain, liver, and bone." (PMID 41383468, 2025). "Next, lung cancer cells transfected with the ACKR2 siRNA or incubated with ACKR2 neutralized antibody markedly abolished CXCL14‐induced cell migration and cell movement, but not CXCR4, and GPR85." (PMID 37056937, 2023).
gastric cancer (148 papers, 2006 to 2026). A primary or metastatic malignant neoplasm involving the stomach. "This consistent expression pattern among these invasion-associated proteins in gastric cancer highlights the significance of the DARPP-32/CXCR4/CXCL-12 axis in promoting invasion." (PMID 39767693, 2024). "It was previously reported that metastasis was associated with the CXCL12/CXCR4 axis in many tumors, including gastric cancer." (PMID 35877436, 2022). "The intensity of CXCR4 in primary gastric cancer lesions was positively associated with TNM staging, LN involvement, and the recurrence/metastasis rate after radical surgery, but negatively with overall survival (OS) and disease-free survival (DFS)." (PMID 35877436, 2022). "Some of these chemokines and receptors, such as CXCL13, CCL4, CCL5, CCR2, CXCR3, and CXCR4, have been experimentally confirmed to be associated with the pathogenesis or prognosis of gastric cancer or other malignancies." (PMID 32685487, 2020). "The risk score was constructed based on 4 genes (GRID2, ATG4D,GABARAPL2, CXCR4), and gastric cancer patients were significantly divided into high-risk and low-risk groups according to overall survival." (PMID 32477008, 2020). "CXCR4 (chemokine receptor type 4): Its expression has been associated with the staging of gastric cancer, being reduced in the majority of gastrointestinal tumors and significantly higher in patients with advanced stages of gastric cancer." (PMID 31616468, 2019). "CXCR4 positivity of primary gastric carcinomas meaningfully was associated with the evolution of peritoneal carcinomatosis." (PMID 29867026, 2018). "shRNA-mediated B7-H3 silencing in the N87 gastric cancer cell line suppressed cell migration and invasion in vitro and in vivo; downregulated metastasis-associated CXCR4; and inhibited AKT, ERK, and Jak2/Stat3 phosphorylation." (PMID 29069741, 2017). "In contrast, a recent study has reported that CXCR4 is associated with lymph node metastasis in gastric cancer." (PMID 24659999, 2014). "VEGFR-3 has been associated with lymphangiogenesis, invasion and metastasis of gastric cancer whilst CXCR4 is associated with stimulation of angiogenesis, lymph node metastasis and peritoneal carcinomatosis." (PMID 24981311, 2014). "It has been reported that metastasis was associated with chemokine signaling through the CXCL12/CXCR4 axis in many tumors, including gastric cancer." (PMID 23936528, 2013). "Cancerous CXCL12 positivity was determined to be an independent prognostic factor for patient survival of gastric cancer and CXCR4 expression was associated with lymph node and liver metastasis of gastric cancer." (PMID 23936528, 2013). "Only 17% of gastric carcinomas showed CXCR4 immunopositive tumour cells, which was associated with higher local tumour extent." (PMID 20386750, 2010). "SDF-1 (CXCL12) is clinically significant as it promotes cancer cell migration, invasion, and metastasis in human gastric cancer through interaction with its receptor CXCR4, and high SDF-1 expression is associated with poor prognosis and increased lymph node metastasis." (PMID 40673273, 2025). "Overexpression of CXCR4 is significantly associated with lymphatic metastasis of gastric cancer." (PMID 38221932, 2024). "Finally, we used the eight immunoregulatory genes coexpressed with PDGFD in gastric cancer and the TCGA dataset to create an immune-associated signature made up of two genes (CXCR4 and TAP1)." (PMID 35509844, 2022). "Furthermore, CXCR2 along with CXCR4 overexpression, was associated with more advanced tumor stages and poorer survival in gastric cancer patients." (PMID 34012923, 2021). "Our findings suggest that B7-H3 and/or its associated molecules, including CXCR4, may be novel targets for anti-gastric cancer therapeutics." (PMID 29069741, 2017).